KL (klotho)
Diseases named in the same sentence as KL in open-access papers (continued):
Sharing a sentence is not in itself a finding about the gene and the disease.
hyperphosphatemia (continued). "Hyperphosphatemia occurs when the homeostasis of phosphate is altered, as described in patients with CKD and in the premature aging syndromes presented in the Klotho mice and FGF23 KO mice." (PMID 28857396, 2017). "In humans with CKD, progressive decreases in klotho occurs in the course of CKD secondary to renal resistance to FGF-23 that results in decreased uFEP values and severe hyperphosphatemia." (PMID 29240673, 2017). "Klotho knockout mice and FGF23 knockout mice display a similar pattern of hyperphosphatemia and extensive vascular calcification." (PMID 27668003, 2016). "It is also not surprising that impairments in the phosphaturic FGF23-klotho system lead to hyperphosphatemia, as shown in genetic mouse models that lack FGF23 (Fgf23−/−) or klotho (kl/kl), which both develop severe ectopic calcifications in the absence of kidney injury." (PMID 40471241, 2025). "The consumption of large amounts of protein may contribute to hyperphosphatemia in CKD, which is known to down-regulate Klotho levels." (PMID 38673780, 2024). "First, unlike animal models, such as adenine-induced and klotho-knocked-out, patients with CKD often have multiple concomitant risk factors (e.g., hyperglycemia, hyperlipidemia, and hyperphosphatemia) for vascular calcification." (PMID 38256228, 2024). "In fact, CKD alters hormonal processes that regulate phosphate levels (intestinal absorption, renal excretion by remaining nephrons, bone metabolism modulated by vitamin D, fetuin-A, Klotho, and fibroblast growth factor 23 (FGF-23); all these processes mentioned favoring hyperphosphatemia." (PMID 37510208, 2023). "Therefore, perturbation of the klotho-FGF-23 endocrine axes, which accompanies hyperphosphatemia, appears to be a major reason for the premature aging effects from PMWCNTs observed in this study." (PMID 37112600, 2023). "The absence of FGF23 or Klotho leads to hyperphosphatemia and resulting premature aging features in mice." (PMID 35928251, 2022). "Lack of klotho in humans or mice leads to severe hyperphosphatemia, increased 1,25(OH)2D and calcium levels, similar to FGF-23 deficiency." (PMID 36246903, 2022). "Lack of Klotho or FGF23 results in hyperphosphatemia and hypervitaminosis D. With age, human renal function often deteriorates, lowering Klotho levels." (PMID 35903083, 2022). "Hyperphosphatemia promotes and triggers the progression of vascular calcification by inducing VSMC apoptosis, leading to the transdifferentiation of VSMCs to osteoblasts, elevating FGF23 levels, and decreasing Klotho expression." (PMID 35080671, 2022). "Given the serological characteristics of hyperphosphatemia that accompanied CKD and CVD in Klotho mutant (kl/kl) mice, we then wondered whether the HP-induced changes in energy metabolism remodeling could also be detected in cardiomyocytes in kl/kl mice." (PMID 32938919, 2020). "Whole-nephron deletion of Klotho in mice results in renal FGF23 resistance, characterized by hypervitaminosis D, hyperphosphatemia, and other phenotypes that may resemble premature aging." (PMID 32982979, 2020). "Recently, FGF23 as a phosphate-regulating hormone has been discovered by the studies on rare hypophosphatemic disorder, whereas Klotho, which subsequently turns out to be a co-receptor for FGF23, is identified in a mouse model showing hyperphosphatemia and multiple aging-like traits." (PMID 33708111, 2020). "In spite of the severely decreased renal function in our patient, the reduction of functional KL with the consequent insensitivity to the action of FGF23 could partially explain the state of persistent and resistant hyperphosphatemia described in the patient." (PMID 31013726, 2019). "In a previous study, klotho knock-out mice exhibited similarities with CKD patients, such as, hyperphosphatemia, ectopic soft tissue calcification, and arteriosclerosis, which suggested CKD might result from a state of klotho deficiency." (PMID 30943913, 2019).
hyperphosphatemia (continued). "Notably, phosphate retention, progressive hyperphosphatemia, rising FGF23 levels and low Klotho expression collectively are observed in human patients with advancing CKD and has been associated with progressive age-associated cardiovascular alterations." (PMID 31546756, 2019). "One might speculate that in addition to PTH resistance, decreased klotho expression from low 1,25(OH)2D3 concentrations could hamper FGF-23 receptor signaling, resulting in hyperphosphatemia and elevated PTH secretion." (PMID 26046642, 2015). "Finally, sKlotho treatment reduced hyperphosphatemia and prevented vascular calcification in mice lacking endogenous Klotho." (PMID 41141519, 2025). "Furthermore, genetic mouse models lacking klotho or FGF23 do not develop severe kidney damage but hyperphosphatemia as well as skeletal muscle wasting and atrophy." (PMID 38791164, 2024). "Furthermore, not only mice with genetic deletion of klotho but also of FGF23 with normal klotho levels develop hyperphosphatemia in the absence of severe kidney damage that is accompanied by skeletal muscle wasting and atrophy." (PMID 39273260, 2024). "The infertile phenotypes found in the gonads of mice lacking Klotho may be secondary effects of hyperphosphatemia and hypervitaminosis D on the disruption of normal endocrine secretion from the hypothalamus, pituitary gland, or adrenal gland." (PMID 37759974, 2023). "MBDs include changes in serum calcium (Ca2+) concentration, increased serum phosphate levels (hyperphosphatemia), reduced serum levels of active vitamin D, secondary increase of parathyroid hormone (PTH), augmented FGF-23 systemic levels, and reduced levels of the antiaging factor Klotho." (PMID 34867481, 2021). "Whether or not hyperphosphatemia and/or reduced klotho levels are the major driver for the cardiac toxicity of high FGF23 in CKD has to be confirmed in further studies." (PMID 34778257, 2021). "Initially, membrane bound renal klotho was considered, exclusively, a high affinity receptor for circulating FGF23 and, therefore, essential for FGF23 phosphaturic actions that attenuate the pro-aging features of hyperphosphatemia: SHPT, systemic inflammation, vascular calcification." (PMID 34950686, 2021). "Klotho is a bona fide longevity gene that, if inactivated, generates a phenotype identical to that of FGF23-null mice, characterized by premature aging, decreased lifespan, elevated 25(OH)D, hyperphosphatemia, ectopic calcification, skin and muscle atrophy, osteoporosis, and hearing loss." (PMID 32899460, 2020). "One of the possible explanations for this discrepancy is that Klotho−/−/VDRΔ/Δ mice on rescue diet used in the current study displayed no mineral disturbance, whereas others used Klotho−/− mice, characterised by 1,25(OH)2D3-mediated hypercalcemia and hyperphosphatemia." (PMID 28900153, 2017). "The significance of Klotho and FGF23 partly lies in the possibility that their dysregulation represents the earliest alterations in CKD and diabetic nephropathy, prior to detectable changes in vitamin D and PTH and much earlier than the occurrence of hyperphosphatemia and hypocalcaemia." (PMID 27668003, 2016). "This improvement, plus the restoration of the growth plate and bone length in Dmp1−/−kl/kl mice compared to Dmp1−/− mice was likely due to a switch from hypophosphatemia to hyperphosphatemia, although the probable local role of Klotho ablation in this phenotypic rescue should not be ignored." (PMID 22879941, 2012). "Compared with Klotho+/+ (WT) mice, KLKO mice exhibited high plasma concentrations of FGF23 and 1,25(OH)2D3, hyperphosphatemia, and hypercalciuria, but not ionized Ca or PTH." (PMID 32026654, 2020). "Collectively, this suggests a cardioprotective effect of Klotho in the setting of CKD that is independent of FGF23 excess, hyperphosphatemia and hypertension." (PMID 30200452, 2018).
atherosclerosis (85 papers, 2005 to 2025). A disease characterized by the build-up of fatty material and calcium deposition in the arterial wall resulting in partial or complete occlusion of the arterial lumen. "In the cardiovascular field, low Klotho can also independently predict macrovascular events or is associated with the degree of atherosclerosis." (PMID 41438297, 2025). "The latest study also discovered that PTX had a positive effect linked to Klotho gene expression in peripheral blood cells, reducing subclinical atherosclerosis progression as measured by carotid intima-media thickness variation." (PMID 39765800, 2024). "Animal studies demonstrate that Klotho deficiency results in vascular calcification, accelerated atherosclerosis, and hypertension." (PMID 38501099, 2024). "A deficiency in the Klotho gene can cause aging in mice, including atherosclerosis and osteoporosis." (PMID 38409304, 2024). "Klotho-deficient mice showed various changes resembling those in patients with premature aging syndromes, such as atherosclerosis, osteoporosis, age-related skin changes, ectopic calcifications, and infertility." (PMID 37894946, 2023). "Klotho-deficient mice have shorter life spans and show remarkable aging characteristics such as atherosclerosis, extensive medial calcification and osteoporosis." (PMID 34696680, 2021). "Blood vessel endothelial cell aging and atherosclerosis, glomerular fibrosis and kidney damage, and skeletal muscle loss significantly increases the risk of degenerative diseases in Klotho-deficient mice [11,23,29,42 to 45]." (PMID 33767585, 2021). "Deficiency of Klotho leads to shortened life span, atherosclerosis, osteoporosis, cognitive and memory impairment, and aging characteristics." (PMID 34938181, 2021). "The reductions in serum and PBCs expression levels of Klotho in CKD patients are independently associated with the presence of for subclinical atherosclerosis." (PMID 34354161, 2021). "Klotho (α-klotho) is such a gene, as indicated in studies of klotho-deficient mice that have a shortened lifespan and demonstrate age-related phenotypes such as atherosclerosis, osteoporosis, and emphysema." (PMID 30595559, 2018). "There are a lot of evidences that Klotho deficiency correlates with the occurrence and development of coronary artery disease, atherosclerosis, myocardial infarction, and left ventricular hypertrophy." (PMID 30671457, 2018). "To conclude, the presented data showed the importance of KLOTHO gene polymorphisms and occurrence of atherosclerosis, coronary artery disease, or left ventricular hypertrophy." (PMID 30671457, 2018). "Previous studies have shown that compared with wild-type mice, KL mutant mice showed obvious age-like phenotypes, including loss of skeletal muscle mass, atherosclerosis, and osteopenia." (PMID 29712948, 2018). "Overexpression of this gene extended life span in mice, and klotho-deficient mouse (klotho −/−) manifested a wide range of aging-related phenotypes, such as short life span, atherosclerosis, and osteoporosis." (PMID 24036517, 2013). "Klotho exerts anti-aging effects, and klotho deficiency results in multiple age-related disorders closely resembling human aging, including atherosclerosis, ectopic calcification and shortened lifespan." (PMID 24340070, 2013). "Klotho has been shown to have a protective effect on endothelial cells by regulating the availability and increased secretion of NO, which helps dilate vessels and regulate blood flow, thus significantly reducing the risk of atherosclerosis." (PMID 38792942, 2024). "Klotho may be of particular interest as a risk factor for CV disease in humans, as atherosclerosis, oxidative stress, and endothelial dysfunction have been shown to be associated with Klotho expression levels in mice." (PMID 38256639, 2024).
atherosclerosis (continued). "Moreover, we recently reported an association between Klotho expression in PBCCs and vascular and systemic inflammation in atherosclerotic vascular disease and with subclinical atherosclerosis in CKD patients." (PMID 37274332, 2023). "A recent study reported that low serum klotho level is associated with larger thickness of carotid artery intima-media, thus it may be considered as an early predictor of atherosclerosis." (PMID 35176041, 2022). "Results of this analyses showed that both serum and PBCs mRNA levels of Klotho were covariates associated with subclinical atherosclerosis, indicating that the levels of both variables are protective factors for the presence of this condition in CKD patients in stage 3–4." (PMID 34354161, 2021). "In addition, both Klotho variables are significantly associated with two markers of subclinical atherosclerosis, ABI and CIMT, independently of cardiovascular risk factors and inflammatory parameters." (PMID 34354161, 2021). "Moreover, Klotho deficiency correlated with the occurrence and development of atherosclerosis, coronary artery disease, myocardial infarction, and left ventricular hypertrophy." (PMID 33123314, 2020). "Moreover, Klotho deficiency has been identified in many disorders such as inflammatory bowel disease, kidney disease, atherosclerosis, cardiac hypertrophy, and remodelling." (PMID 33123314, 2020). "Critically, accumulating experimental, clinical and epidemiologic evidence have shown that Klotho deficiency is associated with a variety of vascular outcomes, such as cardiovascular events and arterial stiffness, vascular calcification and atherosclerosis." (PMID 31546756, 2019). "Deficiency of Klotho leads to a syndrome resembling aging, including a short lifespan; stunted growth and kyphosis; vascular calcification and atherosclerosis; osteoporosis; pulmonary emphysema; cognitive impairment; deafness; and atrophy of skin, muscles, gonads, and many other organs." (PMID 29720929, 2018). "However, serum Klotho levels have been associated with different vascular risk factors in humans, such as atherosclerosis, oxidative stress and endothelial dysfunction 24,25,44,45." (PMID 28076518, 2016). "A role for the human KLOTHO gene in vascular disease also has been suggested by work demonstrating that the same KL-VS allele is associated with increased risk of occult atherosclerosis in a high-risk sample consisting of siblings of individuals with premature CAD." (PMID 16262891, 2005). "(2024) also proposed that the combined detection of FGF23 and Klotho levels can better predict the risk of atherosclerosis in patients with T2DM than the detection of Klotho alone, suggesting that there may be a synergistic or complementary effect between the two." (PMID 41438297, 2025). "Transgenic overexpression of klotho in mice has been shown to extend life span, while conversely, disruption of the KL gene has been associated with an accelerated aging phenotype, which includes atherosclerosis, emphysema, osteoporosis, infertility, and behavioral impairment." (PMID 37107675, 2023). "Interestingly, reduced Klotho serum levels are associated with endothelial dysfunction, oxidative stress, accelerated atherosclerosis, plaque instability with increase in atherosclerosis mediated inflammatory response playing a plausible role in acute cardiovascular." (PMID 37061530, 2023). "However, it is unclear whether circulating Klotho, and its expression in peripheral blood cells (PBCs) are also associated with subclinical atherosclerosis in CKD." (PMID 34354161, 2021). "Therefore, it is safe to assume that Klotho C1818T polymorphism might be associated with the late atherosclerosis." (PMID 30547758, 2018). "This supports the hypothesis of Klotho association with atherosclerosis." (PMID 30671457, 2018). "Exogenous Klotho supplementation delays the development of CKD-accelerated atherosclerosis through reduced vascular calcification and lessening heart failure." (PMID 40119098, 2025).
atherosclerosis (continued). "Low KL levels seem to be correlated with atherosclerosis, and BBR upregulating SIRT1 also increases KL expression, leading overall to a protective condition." (PMID 41228388, 2025). "Recently, studies were conducted on the clinical application of recombinant Klotho for the prevention and treatment of atherosclerosis." (PMID 41517379, 2025). "Recent evidence further implicates reduced Klotho expression in the progression of atherosclerosis, particularly under diabetic conditions." (PMID 40799848, 2024). "Although previous studies reported that Klotho is related to atherosclerosis and longevity in mice, there is a paucity of studies on the association between Klotho levels and cardiovascular mortality in human populations, and the results are conflicting." (PMID 38409304, 2024). "Klotho mutant mice exhibit a range of aging symptoms such as osteoporosis, atherosclerosis, and skin atrophy, accompanied by a shortened lifespan." (PMID 39556550, 2024). "Both FGF23 and the FGF23/Klotho ratio were linearly positively correlated with the occurrence of T2D as well as increased carotid intimal thickness and atherosclerosis in subjects with T2D." (PMID 39272986, 2024). "Low Klotho levels contribute to the upregulation of reactive oxygen species (ROS), exacerbating endothelial damage and promoting atherosclerosis." (PMID 39765800, 2024). "In rodents, Klotho reduces vascular calcification, but there have been few studies of atherosclerosis." (PMID 39272986, 2024). "Our analysis also extended into emerging atherosclerosis markers, such as klotho and pluripotency genes." (PMID 38610757, 2024). "The literature also reports the possibility of perceiving the Klotho protein as a prognostic factor for early atherosclerosis." (PMID 37998729, 2023). "Together with serum, we have also determined Klotho expression levels in PBCCs and in vascular tissue, which have a clear implication with the progression of atherosclerosis." (PMID 37274332, 2023). "Endothelial injury and dysfunction associated with reduced Klotho levels and elevated FGF23 concentrations have been shown to justify the worsening of atherosclerosis in diabetic patients with PAD." (PMID 37061530, 2023). "Although this work provides novel information about the relationship between Klotho and atherosclerosis, we acknowledge several limitations." (PMID 37274332, 2023). "In conclusion, we found that lower Klotho levels are inversely correlated with CIMT values in a group of patients with atherosclerosis and preserved kidney function." (PMID 37274332, 2023). "Deficiency of KL has been correlated with cardiovascular disease, and low expression of KL is considered an early predictor of atherosclerosis." (PMID 38038821, 2023). "Further studies by other authors have documented low serum Klotho levels as an early predictor of atherosclerosis (50 healthy volunteers), and higher plasma Klotho levels are associated with better cognition." (PMID 37894946, 2023). "Further experimental studies are needed to delve into the interactions between Klotho and the progression of the atherosclerosis burden." (PMID 37274332, 2023). "Lower levels of serum Klotho can lead to stiffness in arteries resulting in vascular dysfunction, which, in turn, can assist in predicting atherosclerosis at earlier stages." (PMID 37425590, 2023). "The desirable therapeutic effects of CFNs were recognized by attenuating systemic oxidative stress and inflammatory cell infiltration in plaques when compared to the traditional atherosclerosis suppressor protein klotho." (PMID 36120595, 2022). "Although our study provides novel information about the relationship between Klotho and subclinical atherosclerosis in CKD patients, we acknowledge several limitations." (PMID 34354161, 2021). "The present study aimed to study the relationship between Klotho and subclinical atherosclerosis in a population of patients with moderate to severe CKD." (PMID 34354161, 2021).